HOTAIR (HOX transcript antisense RNA)
Diseases named in the same sentence as HOTAIR in open-access papers (continued):
Sharing a sentence is not in itself a finding about the gene and the disease.
glioma (continued). "Furthermore, we confirmed that the knockdown of HOTAIR inhibited the proliferation, migration and invasion, promoted the apoptosis and induced the cell cycle arrest in G0/G1 phase in glioma cells, indicating that HOTAIR played an oncogenic role in human glioma." (PMID 26183397, 2015). "HOTAIR as a ceRNA against miR-126-5p promotes GLS expression, as suggested by clinical data from human subjects of astrocytomas, oligodendrogliomas, and glioblastomas; as well as from exploratory studies in glioma cell lines, U87 and U251." (PMID 38366205, 2024). "HOTAIR can also repress two crucial target genes, Calcium Binding And Coiled-Coil Domain 1 (CALCOCO1) and zinc finger CCCH-type containing 10 (ZC3H10), directly involved in the modulation of sensitivity to TMZ in U251 glioma cells." (PMID 38887279, 2024). "According to prior research on other diseases, the allelic frequencies of the HOTAIR SNPs rs12826786 and rs920778 were not statistically different between cancer-free controls and glioma patients." (PMID 37776415, 2023). "HOTAIR (HOX Transcript Antisense RNA) could promote NF-kappaB phosphorylation and nuclear translocation by targeting NBXN1, thus induce immune escape for glioma patients." (PMID 37056564, 2023). "As FOSL1 is a key glioma regulator, it is expected that other TRPM7-mediated FOSL1 activations could contribute to glioma pathogenesis, other than HOTAIR and miR-301a-3p." (PMID 36844925, 2022). "HOTAIR can promote the formation of H3K27me3 through the EZH2 protein, silence the transcriptional expression of genes and promote the malignant progression of glioma." (PMID 34082742, 2021). "Glioma tissue (both low-grade and high-grade), as well as glioma cell lines (U867 and U251), had higher HOTAIR expression compared to non-neoplastic brain tissue." (PMID 34322395, 2021). "HOTAIR acts as a negative prognostic factor for various cancers, including glioma, and its abundant expression is closely related to tumor progression." (PMID 33980320, 2021). "HOTAIR has also been shown to promote malignant progression in gliomas and serves as a negative prognostic factor for survival of glioma patients." (PMID 34207158, 2021). "HOTAIR expression in GBMs is significantly higher than that in normal brain tissues and low-grade gliomas and correlated with poor prognosis and glioma molecular subtype." (PMID 30116729, 2018). "To test this, we studied the expression pattern of HOTAIR and HOXA9 in adult and pediatric glioma-derived cell lines by semi-quantitative reverse transcription-PCR (RT-PCR) and qPCR, and found these genes to be frequently co-expressed in glioma." (PMID 29644006, 2018). "Additionally, we further investigated the relevance of HOTAIR as a prognostic biomarker in GBM, and in malignant WHO grade II and III glioma." (PMID 29644006, 2018). "Similarly, significant correlations between HOTAIR and HOXA9 expression were also observed in specific combinations of glioma grades (Portuguese dataset WHO grades II+III, III, III+IV and II+III+IV; French dataset IDH-wt WHO grade III and grade IV)." (PMID 29644006, 2018). "The expression of SNORD47 in Grade IV glioma specimens was significantly inverse with HOTAIR, which is a negative prognostic factor in glioblastoma." (PMID 28410200, 2017). "We measured the expression levels of HOTAIR and SKA2 in 56 human glioma tissues." (PMID 27121316, 2016). "In HOTAIR knock-down glioma cells, unlike expression of the 5′ domain, the expression of the HOTAIR 3′ domain (LSD1 complex-binding domain) did not rescue the cell cycle arrest." (PMID 25428914, 2015). "HOTAIR expression was significantly up-regulated in the glioma tissues (GT) and two glioma cell lines compared with the surrounding non-neoplastic tissues (ST) and normal brain tissues (NBTs), respectively." (PMID 26183397, 2015). "Many lncRNAs could regulate the progression of glioma, like NEAT1, HOTAIR, and GAS5." (PMID 34056009, 2021).
glioma (continued). "Also, HOTAIR expression correlates with angiogenesis via modulation of VEGFA expression, one of the most important factors in tumor angiogenesis, and transmission of this factor to endothelial cells through glioma cell-derived extracellular vesicles." (PMID 33980320, 2021). "Although these results indicate that DNA methylation may regulate HOTAIR expression in GBM, this association was not universal, so other transcriptional regulation mechanisms are involved in glioma." (PMID 29644006, 2018). "Interestingly, HOTAIR may act as a ‘sponge’ of miR-141, thereby modulating expression of SKA2 in glioma." (PMID 27121316, 2016). "Taken together, knockdown of HOTAIR up-regulated miR-326 expression, and further inducing the decreased expression of FGF1, these results provided a comprehensive analysis of HOTAIR-miR-326-FGF1 axis in human glioma and provided a new potential therapeutic strategy for glioma treatment." (PMID 26183397, 2015). "In summary, HOTAIR could regulate the expression of SNORD76 independent of regulation of the expression of GAS5, and SNORD76 caused marked repression of glioma growth in vitro and in vivo." (PMID 25715874, 2015). "Collectively, we suggested that this small nucleolar RNA, SNORD76, could be a tumor suppressor in glioma rather than a monotonous element in response to oncogenic HOTAIR alterations." (PMID 25715874, 2015). "We observed a similar expression pattern for HOTAIRM1 but not for HOTAIR, two HOX lncRNAs involved in glioma biology." (PMID 35563134, 2022). "Taken together, our results strongly suggest that HOTAIR and HOXA9 are concomitantly co-expressed in human gliomas, but not in other cancer types." (PMID 29644006, 2018).
cervical carcinoma (100 papers, 2015 to 2025). A carcinoma arising from either the exocervical squamous epithelium or the endocervical glandular epithelium. "Propofol, an anaesthetic has been shown by several studies to induce apoptosis by specifically downregulating HOTAIR expression and its associated pathways like mTOR pathway, in various cervical cancer cells like HeLa, SiHa as well as in mice models." (PMID 39912983, 2025). "The three SNVs in the HOTAIR gene, rs7958904, rs920778, and rs4759314, have been reported as risk factors appearance of cervical cancer in the Chinese population." (PMID 38157198, 2024). "In summary, SPRY4 and HOTAIR among lncRNAs are promising markers of cervical cancer, which can be used as diagnostic indicators and good markers for prognosis of cervical cancer." (PMID 36890809, 2023). "The third highest tissue expression reported by lncHUB2 for HOTAIR is in the cervix, and HOTAIR has been associated with cervical cancer progression." (PMID 36869839, 2023). "This indicates that the risk-associated allele T is closely related to the expression of HOTAIR, and SNP rs920778 can promote the expression of HOTAIR, thereby promoting the genetic susceptibility to cervical cancer." (PMID 36890809, 2023). "Specifically, rs920778 genotype was analyzed in 215 cervical cancer patients and 430 normal controls and observed that TT genotype of rs920778 was associated with HOTAIR upregulation." (PMID 36438563, 2022). "HPV16 E7 oncoprotein can modulate the expression of HOTAIR in cervical cancer cells, suggesting that E7 oncoprotein was linked to lncRNA HORAIR expression in cervical cancer." (PMID 36438563, 2022). "In patients with cervical cancer, elevated HOTAIR levels are significantly associated with poor prognosis." (PMID 35456001, 2022). "Aberrant HOTAIR expression has also been described in ovarian and cervical cancer, with a powerful association with metastatic progression and poor patient survival." (PMID 33540611, 2021). "It has been shown that the HOTAIR rs7958904 CC genotype associates with the higher cervical cancer risk in comparison to the GG/GC genotypes (OR = 1.57)." (PMID 33028884, 2020). "HOTAIR levels have observed to be consistently high in cervical cancer tissues and associated with lymph node metastasis and reduced overall survival." (PMID 32154165, 2020). "Collectively, a large amount of cervical cancer patients presented abnormal HOTAIR expression, which predicted high cancer risk, resistance to routine therapies and poor prognosis." (PMID 28649178, 2017). "High HOTAIR expression was associated with shorter overall survival in cervical cancer (HR = 3.93, 95% CI = 2.34–6.62, P < 0.001, fixed-effect)." (PMID 28977961, 2017). "In a recent study, we demonstrated that circulating HOTAIR is markedly upregulated in the sera of cervical cancer patients, and this upregulation is associated with advanced tumor stage, invasion of the lymphovascular space, and lymph node invasion." (PMID 28649178, 2017). "Higher serum HOTAIR expression was associated with changes in overall survival times of cervical cancer patients." (PMID 27323817, 2016). "ART caused a significant decrease in cervical cancer cell migration, which was obviously reduced by HOTAIR overexpression." (PMID 27736969, 2016). "In cervical cancer patients, HOTAIR expression is associated with tumour stage and EMT and is associated with a poorer prognosis." (PMID 27323817, 2016). "The association between HOTAIR and cervical cancer has also demonstrated that upregulation of HOTAIR promoted cervical carcinoma cells proliferation, invasion and migration." (PMID 27467165, 2016). "The combined OR was 2.20 (95% CI: 1.35–3.59; P = 0.002), suggesting that the expression level of HOTAIR was associated with tumour size in patients with cervical cancer." (PMID 27897239, 2016).
cervical carcinoma (continued). "The combined HR was 2.56 (95% CI: 1.55–4.22; P < 0.0001), suggesting that the expression level of HOTAIR was a risk factor for OS in patients with cervical cancer." (PMID 27897239, 2016). "In this study, we found a significant relation between HOTAIR rs920778 genotypes and cervical cancer risk." (PMID 27467165, 2016). "HOTAIR expression was a significant prognostic indicator for recurrence in cervical cancer patients (relative risk=5.281; P=0.0493)." (PMID 25405331, 2015). "We found that HOTAIR was highly expressed in cervical cancer and was associated with disease recurrence." (PMID 25405331, 2015). "In the present study, HOTAIR expression was associated with disease recurrence in cervical cancer patients and increased the proliferation, migration, and invasion of cervical cancer cells in vitro." (PMID 25405331, 2015). "Among them, SNP rs920778 in the HOTAIR enhancer gene was strongly associated with cervical cancer." (PMID 36890809, 2023). "Based on a meta-analysis that investigated the connection between HOTAIR polymorphisms and risks of BC, cervical cancer, and ovarian cancer, only rs4759314 was substantially correlated to a lower risk of BC, ovarian cancer, and cervical cancer." (PMID 37776415, 2023). "In our previous study, a single nucleotide variation in HOTAIR was found to be associated with pathology and mortality in colorectal cancer patients, and another study reported an association with cervical cancer and the increased expression of HOTAIR in ovarian cancer stem cells." (PMID 33809601, 2021). "In cervical cancer, limited data suggested that HOTAIR could act as sponge for several miRNAs and cause deregulation of the respective target genes." (PMID 34320988, 2021). "However, the precise role and function of HOTAIR in cervical cancer remained unclear, only a relatively small number of studies have associated HOTAIR with cervical cancer." (PMID 34320988, 2021). "Moreover, the detection of circulating levels of HOTAIR is strongly associated with advanced tumor disease, lymph nodes metastases, and poor survival in cervical cancer patients." (PMID 32397382, 2020). "Moreover, the HOTAIR levels are higher also in the serum of cervical cancer patients and significantly associated with increased tumor size, lymph vascular space invasion, lymph node metastasis, and reduced survival." (PMID 32154165, 2020). "In conclusion, our meta-analysis suggested that lncRNAs may serve as novel predictive factors for prognosis of cervical and high expression HOTAIR was associated with shorter overall survival in cervical cancer." (PMID 28977961, 2017). "Like that in ovarian cancer, HOTAIR polymorphisms have also been found in cervical cancer." (PMID 28649178, 2017). "HOTAIR overexpression was a risk factor for overall survival (OS) of patients with cervical cancer." (PMID 27897239, 2016). "In the present study, we hypothesized that genetic variants in HOTAIR could modulate cervical cancer susceptibility." (PMID 27467165, 2016). "Additionally, multivariate analysis showed that high HOTAIR expression was an independent risk factor for cervical cancer metastasis and poor prognosis." (PMID 27897239, 2016). "In addition, the high expression level of HOTAIR in cervical cancer tissues associated with upregulation of VEGF and MMP-9 expression levels compared with the low expression groups." (PMID 25405331, 2015). "In conclusion, our results suggest that HOTAIR is associated with recurrence in cervical cancer." (PMID 25405331, 2015). "Hence, HOTAIR rs7958904 may affect cervical cancer susceptibility by the modulation of CC cell proliferation." (PMID 33028884, 2020). "In addition, a study including 1,209 patients and 1,348 healthy controls also demonstrated that rs7958904 of HOTAIR might affect cervical cancer susceptibility by modulation of cervical cancer cell proliferation." (PMID 32329235, 2020).
cervical carcinoma (continued). "In addition, the frequency of the rs920778 C HOTAIR allele is reported to be significantly higher in HPV-positive cervical cancer cases while its expression level is observed to be low due to the ability of miR-22 to bind rs920778 C sequence and to suppress the HOTAIR expression." (PMID 32154165, 2020). "However, the reduction of HOTAIR expression among the cervical cancers could be responsible for the loss of such gene silencing and hence HOXD10 upregulation, which demanded further validation." (PMID 28402266, 2017). "To reveal whether HOTAIR circulating in serum is linked to clinicopathological features of cervical cancer, we measured the relative HOTAIR concentrations in serum of 153 patients at different stages of cervical cancer." (PMID 27323817, 2016). "Therefore, analysis of HOTAIR expression in cervical cancer patients may predict the risk of recurrence and, therefore, help guide treatment decisions." (PMID 25405331, 2015). "For example, a small molecule inhibitor of the lncRNA HOTAIR has been shown to inhibit cervical cancer." (PMID 39912983, 2025). "lncRNAs that have been investigated as potential biomarkers for cervical cancer include HOTAIR MALAT1, HIF1A-AS2, PRNCR1 and UCA1." (PMID 39912983, 2025). "Clinically, elevated HOTAIR expression in cervical cancer tissues correlates with advanced tumor stage, lymph node metastasis, and decreased overall survival." (PMID 41195272, 2025). "Propofol inhibits activation of the mammalian target of rapamycin (mTOR)/p70S6K pathway and modulates the HOTAIR/miR-129-5p/ribosomal protein L14 (RPL14) axis by decreasing HOTAIR expression, which subsequently inhibits the growth of cervical cancer cells." (PMID 40129947, 2025). "Consistent with the ceRNA mechanism, the expression of HOTAIR and miR-29b is negatively correlated with each other in cervical cancer." (PMID 39403602, 2024). "In the same way, the knockdown of HOTAIR suppressed tumour growth in vivo and further increased the radiosensitivity of cervical cancer." (PMID 38887279, 2024). "Aberrant expression of HOTAIR strongly induced HIF-1α expression in cervical cancer cells and in mice models exposed to radiation." (PMID 38887279, 2024). "This complex regulatory network underscores HOTAIR’s pivotal role in coordinating these pathways and its significance in cervical cancer progression." (PMID 39273054, 2024). "In cervical cancer, HOTAIR was found to promote EMT and induce chemoresistance via a miR-29b/PTEN/PI3K ceRNA network." (PMID 39403602, 2024). "The overexpression of HOTAIR induces radiation resistance in cervical cancer cells by upregulating HIF-1α expression; however, the mechanism underlying the interaction between HOTAIR and HIF-1α in cervical cancer cells postradiotherapy remains obscure." (PMID 38651153, 2024). "Previous studies also demonstrated that HOTAIR overexpression promotes DNA repair and radioresistance in breast and cervical cancers through different mechanisms." (PMID 39055884, 2024). "HOTAIR overexpression also was shown to promote DNA repair and radioresistance in breast and cervical cancers through different mechanisms." (PMID 39055884, 2024). "Silencing HOTAIR reverted these processes; 3) in cervical cancer, HOTAIR is involved not only in the promotion of proliferation and migration but also in the induction of EMT and cisplatin, paclitaxel, as well as docetaxel resistance." (PMID 38887279, 2024). "This process leads to the sustained activation of both pathways, highlighting a novel regulatory axis involving HOTAIR and HIF1α in cervical cancer." (PMID 39273054, 2024). "And compared with rs920778 CC, HOTAIR mRNA expression was significantly increased in cervical cancer patients carrying rs920778 CT or TT genotype." (PMID 36890809, 2023). "In cervical cancer, HOTAIR promotes cell proliferation, migration, invasion, and autophagy, inhibits apoptosis, stimulates angiogenesis, accelerates cell cycle progression, and induces EMT." (PMID 36924407, 2023).